NFIL3 (nuclear factor, interleukin 3 regulated)
Description:
Acts as a transcriptional regulator that recognizes and binds to the sequence 5'-[GA]TTA[CT]GTAA[CT]-3', a sequence present in many cellular and viral promoters. Represses transcription from promoters with activating transcription factor (ATF) sites. Represses promoter activity in osteoblasts (By similarity). Represses transcriptional activity of PER1 (By similarity). Represses transcriptional activity of PER2 via the B-site on the promoter (By similarity). Activates transcription from the interleukin-3 promoter in T-cells. Competes for the same consensus-binding site with PAR DNA-binding factors (DBP, HLF and TEF) (By similarity). Component of the circadian clock that acts as a negative regulator for the circadian expression of PER2 oscillation in the cell-autonomous core clock (By similarity). Protects pro-B cells from programmed cell death (By similarity). Represses the transcription of CYP2A5 (By similarity). Positively regulates the expression and activity of CES2 by antagonizing the repressive action of NR1D1 on CES2 (By similarity). Required for the development of natural killer cell precursors (By similarity).
Synonyms: E4BP4; IL3BP1; NFIL3A; NF-IL3A
Tractability: PROTAC: UniProt records ubiquitination sites on it; ubiquitination databases record sites on it.
Gene: Protein-coding gene on chromosome 9 (91,408,748 to 91,425,066, reverse strand). Ensembl gene ENSG00000165030.
Subcellular location: Nucleus
Subcellular location (Human Protein Atlas): Nuclear bodies
Gene Ontology:
Molecular function: DNA-binding transcription repressor activity, RNA polymerase II-specific; identical protein binding; protein binding; RNA polymerase II cis-regulatory region sequence-specific DNA binding; RNA polymerase II transcription regulatory region sequence-specific DNA binding; DNA-binding transcription factor activity; DNA-binding transcription factor activity, RNA polymerase II-specific; DNA binding
Biological process: negative regulation of DNA-templated transcription; negative regulation of transcription by RNA polymerase II; circadian rhythm; immune response; natural killer cell differentiation; positive regulation of DNA-templated transcription; regulation of DNA-templated transcription; regulation of transcription by RNA polymerase II; transcription by RNA polymerase II; DNA-templated transcription
Cellular component: RNA polymerase II transcription regulator complex; chromatin; nucleus
Genetic constraint (gnomAD): Loss-of-function variants: 6 observed, 17.01 expected, observed/expected ratio (o/e) 0.35, 90% interval 0.19 to 0.7. The upper end of that interval is the gene's LOEUF score, 0.7, which puts it in group 2 of 6, group 1 being the genes least tolerant of losing a copy. Missense variants: 436 observed, 575.35 expected, observed/expected ratio (o/e) 0.76, 90% interval 0.7 to 0.82. Synonymous variants: 202 observed, 217.4 expected, observed/expected ratio (o/e) 0.93, 90% interval 0.83 to 1.04.
Homologues: Orthologues: chimpanzee NFIL3 (100% identical), macaque NFIL3 (99% identical), pig NFIL3 (90% identical), mouse Nfil3 (84% identical), rat Nfil3 (84% identical), rabbit NFIL3 (80% identical), tropical clawed frog nfil3 (69% identical), zebrafish nfil3 (50% identical), Drosophila melanogaster vri (22% identical), Caenorhabditis elegans atf-2 (16% identical). Paralogues in human: NFILZ (16% identical).
Diseases named in the same sentence as NFIL3 in open-access papers:
NFIL3 is named in the same sentence as 105 diseases in open-access papers, as found by Europe PMC text mining. Sharing a sentence is not in itself a finding about the gene and the disease. The quoted sentences say what the papers report.
breast carcinoma (12 papers, 2014 to 2025). "High NFIL3 expression was associated with better prognosis in breast cancer and ovarian cancer but worse prognosis in colon cancer, consistent with previous studies." (PMID 38356719, 2024). "Concerning overall survival in patients with NFIL3 expression, there was an increased risk in the outcome of Luminal B breast cancer patients that were positive for ERα." (PMID 39765744, 2024). "When hypoxia-related risk factors and clinical relevance were studied in breast cancer, NFIL3 risk scores were identified as independent prognostic indicators for breast cancer patients." (PMID 39765744, 2024). "NFIL3 can enhance cancer-associated inflammation mediated by the NF-κB signaling pathway in breast cancer patients." (PMID 36238290, 2022). "NFIL3 is overexpressed in several cancer types, and is associated with reduced survival in breast cancer." (PMID 25860936, 2015). "NFIL3 expression in breast cancer was found strikingly associated with poor prognosis by Kaplan Meier survival analysis." (PMID 26539561, 2014). "Overall survival analysis showed that TNFAIP6, IFITM2, IFNGR1, and IRF6 expression levels were not significant, whereas IFRD1 (n = 568) indicated a significantly (p < 0.05) increased risk in Luminal A breast cancer patients, along with NFIL3 (n = 219) in Luminal B patients with similar significance." (PMID 39765744, 2024). "The heat map tables show the correlation between immune cell infiltrations and TNFAIP6, IFRD1, IFITM2, IFNGR1, IRF6, and NFIL3 in breast cancer." (PMID 39765744, 2024). "Margin status, American Joint Committee on Cancer (AJCC) stage, hypoxia status, estrogen receptor/progesterone receptor (ER/PR) status, NFIL3, SERPINE1, EGFR, and risk score were identified as independent prognostic indicators for breast cancer patients." (PMID 38500661, 2024). "Surprisingly, we found that the expression of NFIL3 protein was significantly higher in TNBC than in other subtypes of breast cancer, which was contrary to the mRNA levels of the NFIL3 expression pattern in TNBC." (PMID 35180863, 2022). "We found that rescuing the expression of NFKBIA in breast cancer cells with NFIL3 overexpression blocked the rapid translocation of NF-κB from the cytoplasm into the nucleus triggered by NFIL3 overexpression in Hs578T cells." (PMID 35180863, 2022). "Consistently, we analyzed the correlation between NFIL3 and NFKBIA in the TCGA dataset and found that NFIL3 mRNA was positively correlated with NFKBIA mRNA in both breast cancer and pancancer." (PMID 35180863, 2022). "In summary, NFIL3 protein is elevated in TNBCs compared with both normal breast tissues and other subtypes of breast cancer, and promotes the progression of TNBC cells by activating the NF-κB signaling pathway through suppressing the expression of NFKBIA." (PMID 35180863, 2022). "We found that NFIL3 inhibits its own transcription, and thus, downregulated NFIL3 mRNA indicates high expression of NFIL3 protein in breast cancer." (PMID 35180863, 2022). "NFIL3 was found highly expressed in a number of poor prognosis cancers such as glioblastoma multiforme and basal like breast cancer." (PMID 26539561, 2014). "The IRF6 expression level was significantly (p < 0.05) positive in Luminal A patients, and the correlation between NFIL3 gene expression levels and neutrophils was significantly (p < 0.05) positive in every breast cancer subtype, including Basal, Her2, Luminal A, and Luminal B." (PMID 39765744, 2024). "Conversely, NFIL3 had a protective role in the other 3 cancer types, including ovarian cancer (OS: total number = 133, HR = 0.82, Cox P = 0.022104), breast cancer (OS: total number = 155, HR = 0.61, Cox P = 0.000250) (and DSS in lung cancer (DSS: total number = 90, HR = 0.49, Cox P = 0.010186)." (PMID 38356719, 2024).
breast carcinoma (continued). "The A3 and A5 cell lines are not tumor cell lines, but they are malignant and tumorigenic, respectively, indicating that NFIL3 could be a potential immunological and prognostic biomarker for breast cancer." (PMID 39765744, 2024). "In this study, we evaluated the aberrant expression of 32 rhythm genes in breast cancer and identified that the expression of NFIL3 was not only altered in breast cancer tissues compared with normal breast tissues but also significantly different between TNBC and other subtypes of breast cancer." (PMID 35180863, 2022). "On the other hand, IFNGR1, IRF6, and NFIL3 were present in the Basal subtype as well as before tumor formation in the cell line of the model, indicating that they could be good markers for Basal subtype breast cancer patients." (PMID 39765744, 2024). "We next focused on NFIL3 and evaluated the expression of NFIL3 protein between TNBC and other subtypes of breast cancer by using IHC." (PMID 35180863, 2022). "The expression of six rhythm genes, CRY2, NFIL3, PER1, EGR3, NR1D1 and TIMELESS, was significantly changed in breast cancer compared with normal breast tissues." (PMID 35180863, 2022). "We identified that nuclear factor interleukin 3 regulated (NFIL3) expression is significantly altered in TNBC compared with both normal breast tissues and other subtypes of breast cancer." (PMID 35180863, 2022). "A significant (p < 0.05) positive correlation was also observed between ESR1 and IRF6 gene expression levels in Basal and Luminal A breast cancer patients, and there was also a significant (p < 0.05) positive correlation between ESR1 and NFIL3 gene expression levels in Basal breast cancer patients." (PMID 39765744, 2024). "We further compared the mRNA levels of these six rhythm genes between 20 normal breast tissues and 20 breast cancer tissues by using qPCR and confirmed that the aberrant expression of NFIL3 and EGR3 in breast cancer is consistent with the results from the GEPIA database." (PMID 35180863, 2022). "Moreover, we detected the protein levels of NFIL3 and NFKBIA in breast cancer tissues using IHC and revealed that the NFIL3 protein level was negatively correlated with the NFKBIA protein level in breast cancer tissues." (PMID 35180863, 2022).
colitis (8 papers, 2017 to 2025). Inflammation of the colon. "NFIL3 promotes the Th2 lineage while inhibiting the Th17 lineage and suppresses the production of IL-12 p40 in macrophages, which is associated with the progression of colitis." (PMID 36969166, 2023). "Interestingly, nine have been implicated in GI disorders; for example, Nfil3 deficiency has been associated with colitis, NFIL3 is a susceptibility gene for inflammatory bowel disease, and TCF7L2 has been implicated in colorectal cancer." (PMID 34165249, 2021). "NFIL3 is IL-10 inducible and serves a primary function as a IL-12p40 transcriptional repressor that suppresses inflammation in colitis." (PMID 39015676, 2024). "We also observed an attenuated suppressive function of Nfil3-overexpressing Treg cells in a transfer-induced colitis model." (PMID 31311918, 2019). "Next, to investigate the physiological effects of Nfil3-overexpressing Treg cells, we injected Treg cells intraperitoneally into Rag1 knockout (KO) mice, along with naive CD4 T cells, to induce colitis." (PMID 31311918, 2019).
Obesity (7 papers, 2020 to 2025). Accumulation of substantial excess body fat. "NFIL3, a circadian regulator frequently implicated in metabolic pathogenesis, was blunted in obesity, as well as the novel eNOS regulator, Cezanne." (PMID 35600313, 2022). "ROR also promotes the transcription of Nuclear factor, interleukin 3 regulated (Nfil3), which suppresses the transcription of Per and Cry genes and more recently has also been shown to influence intestinal lipid uptake and obesity." (PMID 36034454, 2022). "Compositional change of the commensal bacteria influences the rhythmic expression of NFIL3 in the epithelium, which subsequently controls obesity and insulin resistance." (PMID 33013924, 2020). "In individuals with obesity, NFIL3 mRNA levels are positively correlated with body mass index." (PMID 40177474, 2025). "NFIL3 is highly expressed in the liver, and knocking out the NFIL3 gene enhances insulin sensitivity, reduces fat accumulation, decreases the expression of inflammation-related genes, and mitigates obesity and other HFD-induced metabolic problems." (PMID 40177474, 2025). "However, DBP, PER2, and NFIL3, and in turn many of the downstream genes they govern, all display marked dysregulation in obesity." (PMID 35600313, 2022). "Conclusively, Nfil3 deletion may protect against obesity-related metabolic dysregulation." (PMID 39048678, 2024). "However, in the absence of Nfil3, the GM was altered with an increase in anti-obesity and anti-inflammatory bacterial abundance." (PMID 39048678, 2024).
systemic lupus erythematosus (7 papers, 2014 to 2025). An autoimmune multi-organ disease typically associated with vasculopathy and autoantibody production. "Beyond that, regulatory factor X1 (RFX1) and the nuclear factor interleukin-3-regulated protein (NFIL3, also known as E4BP4) are also reported in our previous study in human lupus CD4+ T cells." (PMID 28785369, 2017). "In humans, the last decade has seen the emergence of a link between NFIL3 and autoimmune diseases such as systemic lupus erythematosus (SLE), inflammatory bowel disorders such as Crohn's disease and ulcerative colitis, as well as rheumatoid arthritis (RA) and juvenile idiopathic arthritis (JIA)." (PMID 38412963, 2024). "NFIL3 has a high expression level in CD4+ T cells of patients with systemic lupus erythematosus (SLE) and suppresses the activation and self-reactivity of T cells and subsequent autoimmune response by downregulating CD40L." (PMID 36969166, 2023). "NFIL3 was highly expressed in CD4+ T cells from systemic lupus erythematosus (SLE) patients compared with those from healthy controls, and NFIL3 inhibited the self-reactivity of T cells by decreasing CD40L expression." (PMID 36439145, 2022). "Interestingly, NFIL3 is highly expressed in T cells that were isolated from patients with systemic lupus erythematosus (SLE); studies using human T cells showed that exogenous NFIL3 hindered T-cell activation and self-reactivity." (PMID 26539561, 2014).
Arthritis (6 papers, 2019 to 2024). Inflammation of a joint. "In this study, the in vivo immunological role of NFIL3 has been characterised, with deficiency in NFIL3 sensitising to arthritis development in mice and in patients." (PMID 30552177, 2019). "NFIL3 mutation can sensitise for arthritis development, in mice and humans, and rewires the innate immune system for IL-1β over-production." (PMID 30552177, 2019). "The potential contribution of this mutation to arthritis susceptibility was demonstrated through a preclinical model, where Nfil3-deficient mice upregulated IL-1β production, with more severe arthritis symptoms on disease induction." (PMID 30552177, 2019). "Parallel studies in mice confirm the arthritogenic potential of NFIL3-deficiency, with Nfil3 knockout mice showing enhanced susceptibility to arthritis induction." (PMID 30552177, 2019). "Furthermore, the deficiency of NFIL3 is associated with juvenile idiopathic arthritis and induces more severe arthritis." (PMID 36969166, 2023). "Global deletion of Nfil3, Cry1 and/or Cry2 worsens disease severity in experimental arthritis models." (PMID 38981514, 2024). "In particular, NFIL3 has been linked to autoimmune disorders such as SLE, inflammatory bowel diseases (Crohn's disease and ulcerative colitis patients), as well arthritis." (PMID 38412963, 2024). "Interestingly, increased production of IL1-β and TNFα has been reported in an Nfil3−/− arthritis model." (PMID 38412963, 2024). "Studies in knockout mice show that in the absence of Nfil3, susceptibility to arthritis is enhanced." (PMID 34492036, 2021).
inflammatory bowel disease (6 papers, 2019 to 2024). A spectrum of small and large bowel inflammatory diseases of unknown etiology. "Additionally, NFIL3 suppresses human inflammatory bowel diseases (IBD) by repressing the transcription of IL-12p40, which mediates T cell inflammatory responses to the enteric microbiota." (PMID 35180863, 2022).
lung carcinoma (6 papers, 2016 to 2024). "Elevated expression of NFIL3 promoted the invasion and migration of lung cancer cells." (PMID 35180863, 2022). "NFIL3 is negatively regulated in four sets of lung cancer and two sets of leukemia." (PMID 36101460, 2022). "NFIL3-PRNP axis has also been proved to increase the migration and invasion ability of lung cancer cells via JNK signaling pathway." (PMID 36213323, 2022). "The most direct evidence of an anti-lung cancer role for NK cells comes from Kras-driven spontaneous lung cancer and cancer cell-injection experiments in mice, in which mice lacking NK cells were generated by Nfil3 knockout or administration of antibodies against NK1.1 or asialo-GM1." (PMID 31293580, 2019).
autoimmune disease (4 papers, 2022 to 2024). A disorder resulting from loss of function or tissue destruction of an organ or multiple organs, arising from humoral or cellular immune responses of the individual to their own tissue constituents. "NFIL3 has been identified as an important immune regulatory factor, and its inhibition can lead to a deficiency in IL-10 expression, potentially resulting in more severe autoimmune diseases." (PMID 39555065, 2024). "Nuclear-factor, interleukin 3 regulated (NFIL3) is an immune regulator that plays an essential role in autoimmune diseases." (PMID 36439145, 2022). "Additionally, the anti-inflammatory effect of NFIL3 in immunity plays a crucial role in autoimmune diseases." (PMID 36969166, 2023).
juvenile idiopathic arthritis (4 papers, 2019 to 2024). Juvenile idiopathic arthritis (JIA) is the term used to describe a group of inflammatory articular disorders of unknown cause that begin before the age of 16 and last over 6 weeks. "A link between NFIL3 deficiency and juvenile idiopathic arthritis (JIA) has been identified in monozygotic twins who both harbored homozygous mutations in NFIL3." (PMID 36439145, 2022).